SOD3 (superoxide dismutase 3)
Diseases named in the same sentence as SOD3 in open-access papers (continued):
Sharing a sentence is not in itself a finding about the gene and the disease.
Fanconi anemia (1 paper, 2017). Fanconi anemia (FA) is a hereditary DNA repair disorder characterized by progressive pancytopenia with bone marrow failure, variable congenital malformations and predisposition to develop hematological or solid tumors. "Of these, three genes (isocitrate dehydrogenase 1 (Idh1), superoxide dismutase (Sod) 2, and Sod3) were upregulated and one gene (Fanconi anemia group C (Fancc)) was downregulated in the HFD + HW group." (PMID 28098768, 2017).
focal segmental glomerulosclerosis (1 paper, 2021). A renal disorder characterized by sclerotic lesions in the glomeruli. "SOD3 knockout mice also had increased proteinuria and renal fibrosis and podocyte injury after adriamycin treatment, an experimental model of focal segmental glomerulosclerosis (FSGS), and that finding was associated with an upregulation of NOX2 and β-catenin signaling." (PMID 33477607, 2021).
fungal keratitis (1 paper, 2017). "The average ratios of the expression levels of the Hmox1, Nos3, Hif1a, Sod2, Sod3, and Gpx2 genes increased more than 2-fold (p < 0.05) at day 1 p.i. in the fungal keratitis model, whereas the expression ratios of the Hif1an and Prdx6 genes decreased more than 2-fold (p < 0.05)." (PMID 28874754, 2017).
gallbladder cancer (1 paper, 2024). "A comparative analysis of differential proteomic data revealed 7 hypermethylated or down-regulated genes (e.g., FBN1, LPP, SOD3) and 61 hypomethylated or up-regulated genes (e.g., HBE1, SNRPF, TPD52), which contributed to the early diagnosis of gallbladder cancer." (PMID 38427106, 2024).
glaucoma (1 paper, 2023). Increased pressure in the eyeball due to obstruction of the outflow of aqueous humor. "For example, our work suggests that PRDX6 and SOD3 might contribute significantly to the endogenous antioxidant response, and therefore, exogenously increasing levels of these proteins might be beneficial in delaying or decreasing glaucoma pathogenesis." (PMID 37875948, 2023).
hepatoblastoma (1 paper, 2024). Hepatoblastoma (HB) is a malignant hepatic tumor and is the most common pediatric liver cancer. "Notably, the transcriptional expression of DNMT3B, followed by PFKFB4 and SOD3, was identified as the most strongly correlated with positive metastatic status in hepatoblastoma." (PMID 39595571, 2024).
histoplasmosis (1 paper, 2012). A disease caused by the fungus Histoplasma capsulatum. "Our results indicate that Sod3 function is a major factor in protecting the yeasts from innate immune cells and in promoting histoplasmosis." (PMID 22615571, 2012).
HIV-1 infection (1 paper, 2024). The type species of lentivirus and the etiologic agent of acquired immunodeficiency syndrome (AIDS). "The overview of the field demonstrates that sources of ROS operational in HIV-1 infection follow similar trends; for example, a decrease in SOD3 activities was found in PLWH plasma." (PMID 38790623, 2024).
hyperlipidemia (1 paper, 2019). "In our studies, hyperlipidemia significantly induced the increase of 4-HNE level in erythrocyte membranes, and it was accompanied by a decrease of SOD2 and SOD3 proteins." (PMID 31089408, 2019).
immune complex disease (1 paper, 2023). "Genes involved in the complement cascade including glycosylphosphatidylinositol-specific phospholipase D1 (GPLD1), carnosine dipeptidase 1 (CNDP1) (in KEGG only), superoxide dismutase 3 (SOD3), and butyrylcholinesterase (BCHE) were also prominent in this immune complex disease." (PMID 37238213, 2023).
Iron deficiency (1 paper, 2022). "Iron deficiency resulted in a lower protein expression of SOD2 (Mn-SOD) and higher SOD3 (extracellular Cu/Zn-SOD), whereas a decreasing trend in SOD1 (intracellular Cu/Zn-SOD) was observed." (PMID 35631204, 2022).
leiomyoma (1 paper, 2024). A well-circumscribed benign smooth muscle neoplasm characterized by the presence of spindle cells with cigar-shaped nuclei, interlacing fascicles, and a whorled pattern. "Two common antioxidant enzymes superoxide dismutase-3 (SOD-3) and catalase have been shown to have significantly reduced activity and mRNA in leiomyoma cells compared to normal myometrial cells." (PMID 38957794, 2024).
liver cancer (1 paper, 2020). An epithelial or non-epithelial malignant neoplasm that arises from the liver. "SOD3 mainly exists in the extracellular space that binds to cell surface proteoglycans, and its overexpression has been implicated in liver cancer." (PMID 32582701, 2020).
lung squamous cell carcinoma (1 paper, 2022). "In lung squamous cell carcinoma, SOD3 expression was not significantly different in patients with different stages." (PMID 35356201, 2022).
lymphoma (1 paper, 2023). A malignant (clonal) proliferation of B- lymphocytes or T- lymphocytes which involves the lymph nodes, bone marrow and/or extranodal sites. "The risk of lymphoma varies with dietary intake of fruits and vegetables in the presence of particular SNPs, such as NOS1, NOS2A, MPO, and SOD3, with more significant results for NOS1." (PMID 37759977, 2023). "Data obtained from this study showed that, especially in DLBCL and FL subtypes, the risk of lymphoma varies with dietary intake of fruits and vegetables in the presence of particular SNPs of some oxidative stress pathway genes, such as NOS1, NOS2A, MPO, and SOD3." (PMID 37759977, 2023).
mood disorder (1 paper, 2024). A cognitive disorder a disturbance in which the person's mood is hypothesized to be the main underlying feature. "Additionally, sufficient production of placental SOD3 may contribute to maternal mood disorders during pregnancy and/or in the immediate postnatal period by inducing the FGF/FGFR axis in pituitary cells." (PMID 39325622, 2024).
myopia (1 paper, 2017). "Such expression changes were evident, particularly in the late myopia dataset where a wide range of genes linked with oxidative stress were either up-regulated (GPX1, GSTA3, MT-4, APOA1, OTUB, PTGDS, HSPB1, HSPB2) or down-regulated (XHD, SLC40A1, TF, SOD3, HPGDS, BCMO1)." (PMID 28852117, 2017).
Oral Squamous Cell Carcinoma (1 paper, 2022). "In contrast, in oral squamous cell carcinoma (OSCC), a tumor with SOD3 highly expressed cancer cells is related to higher lymph node metastasis than a tumor without SOD3 expression." (PMID 36359248, 2022).
Parkinson (1 paper, 2022). "To further confirm that anti-Parkinson’s activities of HLEA-P1 is mediated by de-activating IIS pathway which, in turn, allows DAF-16 to enter the nucleus and activate its target genes, we measured the expressions of mRNAs of sod-3, hsp-16.1, hsp-16.2, and hsp-12.6 in C. elegans PD models." (PMID 36582526, 2022).
periapical periodontitis (1 paper, 2025). Inflammation of the periapical tissue. "Genetic polymorphisms in SOD2 and SOD3 genes can influence the OHRQoL response in patients with asymptomatic periapical periodontitis." (PMID 40261148, 2025). "Polymorphisms in the SOD2 and SOD3 genes influenced the OHRQoL of patients with asymptomatic periapical periodontitis who are undergoing root canal treatment." (PMID 40261148, 2025). "Consequently, our study proposed the hypothesis that genetic polymorphisms in SOD2 (rs5746136, rs4880, and rs10370) and SOD3 (rs2855262 and rs13306703) could modulate the impact of OHRQoL in patients with asymptomatic periapical periodontitis." (PMID 40261148, 2025).
Plasmodium falciparum malaria (1 paper, 2024). Malaria resulting from infection by Plasmodium falciparum. "We observed that the level of superoxide dismutase 3 (SOD3) was significantly elevated in both Plasmodium falciparum malaria patients and mice infected with four parasite species." (PMID 38851821, 2024).
prediabetes (1 paper, 2025). "Further examination revealed that SOD3 levels were reduced in both the prediabetes and T2DM groups when compared to controls." (PMID 40362367, 2025). "This study evaluated miR-21 and miR-30b expression alongside SOD3 and CAT plasma levels in individuals aged ≥ 65 years (n = 126) categorized into control (n = 38), prediabetes (n = 37), and T2DM (n = 51) groups." (PMID 40362367, 2025). "In conclusion, our study identifies reduced plasma SOD3 levels as significantly linked with CMD in elderly patients, particularly those with T2DM, though its lack of significant reduction in prediabetes limits its early diagnostic utility." (PMID 40362367, 2025). "In the subgroup analysis of patients with prediabetes and T2DM, a moderate negative correlation between SOD3 levels and HDL concentration was observed only in the prediabetes group." (PMID 40362367, 2025).
pregnancy toxemia (1 paper, 2025). "PCR-DNA sequence analysis revealed that the amplified fragments of IL-6 (627 bp), IL-8 (264 bp), FASN (381 bp), SOD3 (393 bp), HMOX1 (460 bp), and ACACA (477 bp) differed between healthy goats and those affected by pregnancy toxemia (PT)." (PMID 41012815, 2025).
pulmonary TB (1 paper, 2015). "We have also explored the specifically expressed serum proteins in TB patients by iTRAQ-2DLC-MS/MS, and found serum protein S100A9, SOD3, and MMP9 as new potential diagnostic biomarkers for pulmonary TB." (PMID 26198726, 2015).
respiratory infection (1 paper, 2012). "In Phox(+/+) mice, SOD3(+) Histoplasma yeasts survive and establish respiratory infection as evidenced by the increasing fungal burdens over the first 8 days." (PMID 22615571, 2012). "Without Sod3, Histoplasma yeasts are attenuated in their ability to establish respiratory infections and are rapidly cleared with the onset of adaptive immunity." (PMID 22615571, 2012).
retinal (1 paper, 2021). "The important role of SOD3 is further underscored by our observation of a significant increase in its level in several retinal degenerative models." (PMID 34679728, 2021).
sarcoma (1 paper, 2024). A usually aggressive malignant neoplasm of the soft tissue or bone. "SOD3 overexpression inhibits sarcoma cell proliferation, migration and metastasis." (PMID 38212774, 2024).
silicosis (1 paper, 2018). Silicosis is a respiratory disease caused by breathing in (inhaling) silica dust. "PH and silicosis were induced in wild-type and Sod3−/− mice through intratracheal injection of crystalline silica at dose 0.4 g/kg." (PMID 30453980, 2018).
skin aging (1 paper, 2022). The gradual irreversible changes in structure of skin that occur as a result of the passage of time.. "According to these results, we demonstrated the association of SOD3 with ECM integrity and the prevention of skin aging." (PMID 35624792, 2022). "Based on these results, we propose that SOD3 prevents and retards skin aging by reducing the intracellular ROS levels and collagen breakdown, while promoting collagen production." (PMID 35624792, 2022). "Based on these results, we hypothesized that SOD3 most likely affects intrinsic skin aging." (PMID 35624792, 2022). "Therefore, SOD3 may play a role in delaying or preventing skin aging." (PMID 35624792, 2022). "Given that SOD3 reduces collagen degradation and increases collagen production in fibroblasts under 3D culture conditions in the absence and presence of TNF-α, we propose that SOD3 has an effect of delaying both intrinsic and extrinsic skin aging." (PMID 35624792, 2022). "Although these results were for blood, they support the possibility that SOD3 expression, but not SOD1 and SOD2, is significantly altered with skin aging." (PMID 35624792, 2022).
skin cancer (1 paper, 2020). "ATOX1, which donates copper ions to SOD3, seems to have a cell line-dependent expression that is especially high in skin cancer cell lines (it is unclear if it is skin cancer cell-specific or also observed in normal skin cells)." (PMID 32756515, 2020).
spinocerebellar ataxia type 2 (1 paper, 2017). A subtype of type I autosomal dominant cerebellar ataxia (ADCA type I) characterized by truncal ataxia, dysarthria, slowed saccades and less commonly ophthalmoparesis and chorea. "Spinocerebellar ataxia type 2 patients had significantly lower SOD3 enzymatic activity than the control group." (PMID 28659860, 2017).
squamous cell carcinoma (1 paper, 2022). A carcinoma arising from squamous epithelial cells. "The ratio of early apoptosis induced by anti-cancer drugs was 10.5% in normal cells, 35.1% in squamous cell carcinoma and 36.9% in adenocarcinoma.The SOD3 high expression was associated with poor survival probability by multivariate analysis (HR: 1.006, 95% CI 1.002–1.011, p=0.006)." (PMID 35356201, 2022).
stomach adenocarcinoma (1 paper, 2019). "In the stomach adenocarcinoma dataset, strong positive correlations in gene expression were identified between members of the small HSP family, including HSPB2, HSPB5 (CRYAB), HSPB6, HSPB7 and HSPB8, as well as the HSP40 family member DNAJB5, with superoxide dismutase (SOD3)." (PMID 30578123, 2019).
thymoma (1 paper, 2022). A neoplasm arising from the epithelial cells of the thymus. "Previous studies in immunocompetent mice with EG-7 tumors (a thymoma) showed that the forced expression of SOD3 in neoplastic and endothelial cells correlated with enhanced perivascular levels of laminin α4-containing isoforms." (PMID 35267534, 2022).
thyroid benign tumors (1 paper, 2015). "While the expression of the SOD3 enzyme is relatively stable in normal tissues, a significant increase in sod3 mRNA levels has been observed in rat thyroid benign tumors with sequential downregulation of expression in carcinogenesis that corresponds to the degree of differentiation of the cells." (PMID 26550576, 2015).
thyroid tumor (1 paper, 2017). A benign or malignant neoplasm affecting the thyroid gland. "Stromal SOD3 had a stimulatory effect on cancer cell growth and an inhibitory effect on cancer cell migration, thus indicating that SOD3 might be a novel player in thyroid tumor stroma." (PMID 28216675, 2017).
Tinnitus (1 paper, 2020). Tinnitus is an auditory perception that can be described as the experience of sound, in the ear or in the head, in the absence of external acoustic stimulation. "Notably, we identified KCNN3, SOD3, MUC4, GALR1, and WDR45B, which are implicated in auditory function, as differentially methylated associated with self-reported tinnitus." (PMID 33192958, 2020). "Notably, tinnitus symptom analyses identified regions with differential methylation in genes KCNN3, MUC4, GALR1, SOD3, and WDR45B (in the low vs. high cumulative blast exposed groups." (PMID 33192958, 2020).
transient cerebral ischemia (1 paper, 2020). "Thus, our findings suggested that transient cerebral ischemia interacts with Aβ infusion to worsen cognitive function through the enhancement of oxidative stress by increasing NADPH oxidase activity and p22phox and p40phox mRNA expression, and lowering the SOD3-mediated antioxidant defense." (PMID 32264971, 2020).
trichinellosis (1 paper, 2022). "A high upregulation of antioxidant defence enzymes in the NC, out of which GPX3 and SOD3 show extracellular location, well explains another long-known phenomenon of trichinellosis being accompanied by an increase in the antioxidant activities in the muscles and blood of infected animals." (PMID 36478989, 2022).
viral hepatitis (1 paper, 2015). An acute or chronic inflammation of the liver parenchyma caused by viruses. "To investigate whether SOD enzymes contribute to viral hepatitis, we infected Sod1−/−, Sod2+/−—a commonly used model for Sod2 deficiency —and Sod3−/− mice with LCMV and monitored the course of disease." (PMID 26588782, 2015).
cancer (58 papers, 2011 to 2025). A tumor composed of atypical neoplastic, often pleomorphic cells that invade other tissues. "In this study, we report a breakthrough in uncovering the role of SOD3 derived from cancer-associated fibroblasts (CAFs) in LUAD." (PMID 41028519, 2025). "One of the mechanisms proposed for the association between SOD3 and cancer is through the accumulation of circulating ROS, which generates an imbalance of SOD3 in the cell, cellular signaling, and transcription factors and gives rise to tumorigenesis." (PMID 39589950, 2024). "The location of the SOD3 gene on chromosome 4 (4p15.1–4p15.3) is considered a critical point for the loss of heterozygosity (LOH) in cancer." (PMID 39589950, 2024). "The SOD3’s human ortholog is implicated in T cell infiltration, while its down-regulation during tumour development contributes to cancer progression." (PMID 39342330, 2024). "Loss of SOD3 in tumor tissues increases oxidative stress, a factor linked to various aspects of cancer progression." (PMID 39430913, 2024). "On the other hand, association studies on different cancers focusing on other variants of the SOD3 gene have shown contradictory results." (PMID 39589950, 2024). "In contrast, an overexpression of mRNA of SOD3 correlates with increased benign growth and is associated with apoptosis induction and the death of cancer cells." (PMID 38201509, 2023). "Extracellular superoxide dismutase (SOD3) induces laminin α4 expression in tumor blood vessels, which is associated with enhanced intratumor T cell infiltration in primary human cancers." (PMID 35267534, 2022). "Low expression of extracellular superoxide dismutase (EcSOD or SOD3) has been associated with poor outcomes and increased metastatic potential in multiple types of cancer." (PMID 30941174, 2019). "Various studies have demonstrated cancer growth suppression caused by supraphysiological SOD3 overexpression in vitro and in vivo." (PMID 27293512, 2016). "The potential role of SOD-3 is consistent with previous findings that violacein can cause oxidative stress in human cancer cell lines." (PMID 25295516, 2014). "Low SOD3 levels are associated with increased cancer incidence and poor prognosis." (PMID 41154660, 2025). "Some variants of the SOD3 gene likely contribute to a decrease in its expression, which could be related to cancer." (PMID 39589950, 2024). "Low levels of SOD3 are associated with a higher incidence of cancer and poor prognosis." (PMID 36555458, 2022). "One gene involved in free radical scavenging, SOD3, was downregulated, whereas the genes associated with cell cycle or cancer, including GADD45B, ID1, KLF10, CSRNP1, and TM4SF1, were upregulated in F. nucleatum-infected GF(P22) cells when compared to F. nucleatum-infected GF(P4) cells." (PMID 29190775, 2017). "The presented hypothesis suggesting increased aggressiveness of cancer cells caused by decreased SOD3 mRNA expression requires a mechanistic explanation." (PMID 27293512, 2016). "Its expression levels and genetic variations can influence cancer risk, progression, and response to therapy, underscoring the importance of SOD3 in cancer biology, and its suppression in Asian PTC patients may contribute to heightened susceptibility by deregulating key oncogenic pathways." (PMID 40558258, 2025). "SOD3, HYOU1, and PPFIA2 show the strongest association with both racial differences and survival, indicating a potential role in racial disparities in cancer outcomes." (PMID 40558258, 2025). "It is reduced in several cancers (such as pancreatic cancer), and the overexpression of SOD3 can decrease the growth and invasiveness of cancer cells and reduce the accumulation of hypoxia-inducible factors." (PMID 40095546, 2025). "Together, these findings underscore the importance of dissecting cell-type-specific roles of SOD3 in distinct tumor microenvironments to understand its implications in cancer biology." (PMID 41028519, 2025).